C3orf18 (chromosome 3 open reading frame 18)
Synonyms: G20
Tractability: Antibody: UniProt predicts a signal peptide or a membrane-spanning region. PROTAC: ubiquitination databases record sites on it.
Gene: Protein-coding gene on chromosome 3 (50,558,025 to 50,573,568, reverse strand). Ensembl gene ENSG00000088543.
Subcellular location: Membrane
Subcellular location (Human Protein Atlas): Cytosol
Gene Ontology:
Cellular component: membrane
Genetic constraint (gnomAD): Loss-of-function variants: 12 observed, 13.66 expected, observed/expected ratio (o/e) 0.88, 90% interval 0.56 to 1.42. The upper end of that interval is the gene's LOEUF score, 1.42, which puts it in group 5 of 6, group 1 being the genes least tolerant of losing a copy. Missense variants: 196 observed, 209.9 expected, observed/expected ratio (o/e) 0.93, 90% interval 0.83 to 1.05. Synonymous variants: 80 observed, 85.78 expected, observed/expected ratio (o/e) 0.93, 90% interval 0.78 to 1.12.
Homologues: Orthologues: chimpanzee C3H3orf18 (98% identical), pig C3orf18 (92% identical), dog C3orf18 (91% identical), rabbit C3orf18 (86% identical), rat C8h3orf18 (85% identical), mouse 6430571L13Rik (84% identical), guinea pig C3orf18 (80% identical), zebrafish C6H3orf18 (54% identical), tropical clawed frog C3orf18 (48% identical). Paralogues in human: SMIM29 (27% identical).
Diseases named in the same sentence as C3orf18 in open-access papers:
C3orf18 is named in the same sentence as 3 diseases in open-access papers, as found by Europe PMC text mining. Sharing a sentence is not in itself a finding about the gene and the disease. The quoted sentences say what the papers report.
autism (1 paper, 2022). Persistent deficits in social interaction and communication and interaction as well as a markedly restricted repertoire of activity and interest as well as repetitive patterns of behavior. "In the severe autism group the AMs associated with IGs of “Language severe” and “IQ severe” are identical with the exception of the “Gene silencing” AM found only in the “IQ severe” due to the IG C3orf18 and in total have 36 common AMs." (PMID 36117207, 2022).
C3orf18 also shares sentences with these, for which no sentence is quoted: infection (1 paper); neurological diseases (1).